BRCA1 (BRCA1 DNA repair associated)
Diseases named in the same sentence as BRCA1 in open-access papers (continued):
Sharing a sentence is not in itself a finding about the gene and the disease.
breast cancer (continued). "A strong correlation between the overexpression of DNA helicase genes and HRD was found both in BRCA1/2-mutated breast cancer as well as in BRCA1/2 wild-type breast cancers." (PMID 35855837, 2022). "Currently, approximately 40% of familial breast cancer risk is explained by a combination of common low-penetrance variants, together with coding rarer variants in predisposition genes, such as BRCA1, BRCA2, PALB2, ATM, and CHEK2 that confer higher risks." (PMID 35884425, 2022). "Immunohistochemical profiles of the BRCA1-mutation breast cancer are featured by expression of cytokeratin (CK) 5/6 and CK14, contributing to the increasing risk of breast cancer." (PMID 36193432, 2022). "BRCA1/2 are high-risk breast cancer susceptibility genes with 11–12-fold elevated relative risks in the general population for women." (PMID 35409110, 2022). "LST, LOH, and TAI genomics scars detection using MyriadMyChoice genomic test were found in TNBC with BRCA1/2 mutations, and then in the other breast cancer subtypes including ER+/HER2-." (PMID 35158866, 2022). "The penetrance estimates for individuals with a pathogenic BRCA1 or BRCA2 variant range from 45 to 85% for breast cancer and from 10 to 65% for ovarian cancer, some of which can be explained by a polygenic background." (PMID 35983412, 2022). "Women carrying pathogenic germline variants (PVs) in the BRCA1/2 genes face elevated risks of developing breast cancer (BC) and ovarian cancer (OC)." (PMID 36536421, 2022). "Of the different molecular breast cancer subtypes, triple-negative breast cancers reportedly common among younger women and African-Americans, are frequently characterized by BRCA1 mutations." (PMID 36942145, 2022). "In Hong Kong, the Hong Kong Hereditary Breast Cancer Family Registry helps to archive the incidence of hereditary mutations for high-risk breast and ovarian cancers, including BRCA1/2 mutations." (PMID 35924163, 2022). "Almost 10% of breast cancer cases are hereditary and mostly related to BRCA1 or BRCA2 gene mutations; both were initially characterized and sequenced more than 25 years ago and since then have become the most thoroughly studied genes in cancer biology." (PMID 35402282, 2022). "For example, the lifetime risk of breast cancer development in women carrying BRCA1/2 is estimated to be 72 and 69%, respectively." (PMID 35804947, 2022). "Approximately 5–10% of breast cancer cases are hereditary, and BRCA1/2 mutations are present in up to 30% of patients with hereditary breast cancers." (PMID 34467476, 2022). "Lifetime breast cancer risk for males with BRCA1/2 alterations is approximately 7%, 80 – 100 times that of the general male population." (PMID 35933387, 2022). "We also observed this in a genetically engineered K14cre;Brca1F/F;Trp53F/F (KB1P) mouse model for BRCA1-mutated breast cancer." (PMID 36467895, 2022). "Most carriers of the pathogenic variant of BRCA1 or BRCA2 with luminal breast cancer in stage I-II (unilateral breast cancer) benefited from RRBM-RRBSO." (PMID 36580360, 2022). "Some studies in breast cancer showed that targeting RNA splicing with an inhibitor, pladienolide B, reduced the occurrence of BRCA1 mutations that promote acquired resistance in breast cancer." (PMID 36010871, 2022). "While one of the best examples of a breast cancer susceptibility gene that is frequently silenced in sporadic breast tumors is the BRCA1 gene, CpG hypermethylation of BRCA1 associated with DNMT 3b overexpression has been reported." (PMID 36185256, 2022). "It is a 4 base pair deletion of exon 18 of BRCA1 mRNA and is considered pathogenic for breast cancer." (PMID 35950060, 2022). "Patients with germline BRCA1/2 mutations have an increased lifetime risk of breast cancer, as well as ovarian, pancreatic, and prostate cancer." (PMID 35626017, 2022). "Studies of breast cancer susceptibility genes in African populations are scarce and have mainly focused on BRCA1 and BRCA212." (PMID 35039564, 2022).
breast cancer (continued). "Since we included high-risk clinical factors, the mutation frequency of BRCA1 in our cohort was 9.8% (113/1151), which was more than in unselected breast cancer populations, accounting for approximately 5%, according to the Cancer Genome Atlas." (PMID 34403063, 2022). "BRCA1 is a well-known breast cancer risk gene, involved in DNA damage repair via homologous recombination (HR) and replication fork protection." (PMID 36362151, 2022). "For instance, the age of onset of breast cancer in Japanese patients harboring germline mutations in BRCA1/2 was lower than the age of onset in patients with intact BRCA1/2, with women younger than 40 years of age having basal or basal-like tumors." (PMID 36685821, 2022). "In an animal model of mice with transplanted genetically engineered BRCA1-deficient (BRCA1−/−) breast cancer, the animals treated with NVB had significantly smaller tumors and lived almost three times longer than those treated with vehicle." (PMID 36613762, 2022). "When recombinant OPG (OPG-Fc), a RANKL inhibitor like denosumab, was used for inhibition of RANKL in mice with a Brca1 mutation, the authors also observed reduced mammary tumor growth." (PMID 35418083, 2022). "As a second line of evidence, we analyzed the dependency status of BRCA1/2‐deficient breast cancer cells to TSG101 expression in the DepMap database." (PMID 36124865, 2022). "ATM and CHEK2 are examples of moderate-penetrance genes with lower lifetime risk of developing breast cancer as compared to the high-penetrance genes BRCA1 and BRCA2, and these moderate-penetrance genes account for around 6% of HBC." (PMID 35625741, 2022). "The pattern of Breast Cancer Genes 1 (BRCA1) and 2 (BRCA2) mutations in Hereditary Breast Ovarian Cancer (HBOC) families varies widely among different populations." (PMID 36230639, 2022). "BRCA1/2 mutations which increase breast cancer risk were associated with better overall survival among triple-negative breast cancer women." (PMID 36064556, 2022). "In one meta-analysis, breast cancer risk for mutation in BRCA1 and BRCA2 was 57% and 49% respectively." (PMID 35163783, 2022). "Specially in women, BRCA1 or BRCA2 mutations result in a 57-65% or 45-55% risk of developing breast cancer by age 70 years, and a lifetime risk of 39-44% or 11-18% of developing ovarian cancer, respectively." (PMID 36463302, 2022). "It has been shown that most hereditary breast cancers are associated with abnormal BRCA1 and BRCA2 genes." (PMID 36359297, 2022). "It has also been shown that smoking for at least 5 years prior to a first pregnancy increases the risk of developing breast cancer in BRCA1/2 mutation carriers." (PMID 35362092, 2022). "Women with a pathogenic germline mutation in the BRCA1 or BRCA2 gene face a high risk of developing breast cancer (BC) and ovarian cancer (OC)." (PMID 35172875, 2022). "Comparative genomic hybridization arrays were used to characterized copy-number (CN) profile of BRCA1/2 mutated breast cancers and predict the benefit from chemotherapy." (PMID 35158866, 2022). "Recent estimates have shown that approx. 70% of individuals with BRCA1 mutations will develop breast cancer by the age of 70." (PMID 35406503, 2022). "BRCA1, a breast cancer susceptibility gene related to cell cycle control, is also important for Nlp-mediated centrosome localization." (PMID 35719990, 2022).
breast cancer (continued). "Regarding men with mutations in the BRCA2 gene, as well as BRCA1 mutations (although with lower associated risks), they also have a higher risk of developing cancer, namely breast cancer and prostate cancer." (PMID 35805026, 2022). "Damaged DNA cannot be repaired by homologous recombination repair in cancer cells with mutated breast cancer susceptibility genes 1 or 2 (BRCA1/2)." (PMID 36045677, 2022). "The protective role of RRBSO in patients with luminal breast cancer increased with their age at diagnosis, stage of the disease, and was impacted by the type of pathogenic variant (BRCA1 or BRCA2)." (PMID 36580360, 2022). "Among 37 types of BRCA1/2 mutation variants identified in the OV cohort, 34 of them have previously been identified in our local breast cancer cohort." (PMID 35608067, 2022). "The probability of dying from breast cancer and distant metastases was considerably higher for BRCA1 and BRCA2 mutation carriers." (PMID 36140642, 2022). "Phase I trials of olaparib, a PARP inhibitor, and capivasertib in BRCA1/2 and non-BRCA1/2 mutated breast cancer patients are ongoing." (PMID 36010585, 2022). "In approximately 63% of patients with breast cancer related to the pathogenic variant BRCA1 or BRCA2, genetic testing was performed after surgery of the primary cancer, with 62% of these patients also undergoing a primary breast-conserving treatment (BCT)." (PMID 36580360, 2022). "BRCA1 c.2635G > T, a reported mutation among Hong Kong Chinese patients, patients with breast cancer from Malaysia, and breast and/or ovarian cancer patients from Singapore." (PMID 35918668, 2022). "Germline mutations in BRCA1 or BRCA2 exist in ~2–7% of breast cancer patients, which has led to the approval of PARP inhibitors in the advanced setting." (PMID 35538088, 2022). "Breast cancer unaffected and affected women with a pathogenic variant in the BRCA1 or BRCA2 gene were psychologically evaluated immediately before (T0), 6 to 8 weeks (T1) and 6 to 8 months (T2) after the disclosure of their genetic test results." (PMID 36536421, 2022). "We studied matched primary and recurrent breast cancers from 13 subjects, nine BRCA1 and four BRCA2 pathogenic variant carriers." (PMID 36344544, 2022). "Approximately, 1 in 10 women with breast cancer diagnosed under 40 years are carrying a BRCA1 or BRCA2 mutation." (PMID 35062994, 2022). "Altogether, these data show that the aminoglycoside G418 induces readthrough of a naturally occurring BRCA1 nonsense mutation in a breast cancer cell line, restoring at some extent not only its FL form but also its function." (PMID 35837282, 2022). "Meta-analysis of these studies of 108,699 unselected breast cancer cases showed that 3.4% of breast cancers occurred in patients with a germline pathogenic variant of BRCA1 or BRCA2 (95% CI 2.5–4.7)." (PMID 35805038, 2022). "This study also reported that distant metastasis, aggressiveness, and protein interactions in many biological pathways are changed in BRCA1/2-mutated condition when compared with BRCA1/2-wild-type breast cancer samples." (PMID 35045088, 2022). "Several PARP inhibitors are currently approved as monotherapies for the treatment of locally advanced or metastatic breast cancer for patients, with breast cancer harboring germline BRCA1/2 mutations or HER2-negative receptor status." (PMID 35954325, 2022). "We identified putative CNVs in up to 31 putative gene regions that were associated (unadjusted P < 0.01) with breast cancer risk for BRCA1/2 pathogenic variant carriers, with CNVs at 15 of these regions present in a human CNV map10." (PMID 36203093, 2022).
breast cancer (continued). "In a mouse model of BRCA1-associated breast cancer, AhR was found to transcriptionally induce the EGF receptor ligand, Amphiregulin, driving tumor growth and macrophage infiltration." (PMID 36588678, 2022). "To date, BRCA1/2 has been very well studied in breast cancer and gynecological oncology, and BRCA2 mutation carriers have been described to be significantly associated with an elevated risk for prostate cancer, colorectal cancer and urothelial carcinoma." (PMID 35372080, 2022). "Together, these results indicate that the synergistic cytotoxicity of combined EZH2/ATM inhibition in BRCA1-deficient mouse mammary tumor cells is mediated by apoptosis." (PMID 35715861, 2022). "For instance, the ectopic expression or endogenous activation of heterochromatin-encoded satellite RNA phenocopied BRCA1-deficient cells and promoted breast cancer formation." (PMID 35327946, 2022). "Inclusion of these polymorphisms into screening panels results in a 40 to 50% increase in breast cancer risk detection among women, and a 5 to 15% increase in detection among BRCA1/2-negative females." (PMID 35853889, 2022). "Inheritance of a BRCA1 or BRCA2 mutation greatly increases lifetime risk of breast cancer and ovarian cancer." (PMID 35625955, 2022). "In breast cancer, on the other hand, a more immunosuppressive phenotype of BRCA1-mutated tumors was observed compared to BRCA2-mutated tumors." (PMID 36077694, 2022). "Data on breast cancer patients carrying mutations in BRCA1/2 genes are considerably limited, but case series descriptions indicate that GnRHa is effective in these patients during chemotherapy." (PMID 35887761, 2022). "Families with both breast and ovarian cancer history were more likely to carry BRCA1/2 mutation than those with either a family history of breast cancers or family history of ovarian cancer history (p value < .001)." (PMID 35608067, 2022). "Basal-like breast cancer, often referred to as TNBC due to its lack of ER, PR, and HER2 expression, is the most common subtype amongst patients with breast cancer gene 1 (BRCA1) mutations (early-onset) and African American women." (PMID 36358806, 2022). "Among all patients with breast cancer, approximately 5% carry BRCA1/2 germline mutations, and this percentage is similar in Chinese and white patients with breast cancers." (PMID 35380032, 2022). "Several studies have reported on the SNPs or mutations of the BRCA1 gene with regard to individuals with breast cancer in many countries." (PMID 36942145, 2022). "Since the prevalence of breast cancer increases drastically in individuals with BRCA1/2 mutation, we performed a collinear analysis of the FOX family and BRCA1/2 gene mutations in breast cancer patients based on data from TCGA." (PMID 36292640, 2022). "Studies show that less than 10% of women choose to become pregnant after a breast cancer diagnosis but almost twice as many in the population of BRCA1/2 gene mutation carriers (19%)." (PMID 35887761, 2022). "Specifically, a healthy woman who harbor germline mutations of BRCA1/2 have a 60–70% increased risk of breast cancer development and a 15–40% increased risk to develop ovarian cancer." (PMID 36284291, 2022). "Recently, the BRCA1-associated ring domain (BARD1), that partners BRCA1 in DNA repair, has been confirmed as a moderate-risk breast cancer susceptibility gene." (PMID 35595798, 2022). "SUMOylation of breast cancer type 1 (BRCA1) after genotoxic stress is involved in DNA damage repair, and BRCA1 mutations are linked to a high risk of breast cancer and ovarian cancer." (PMID 35408841, 2022). "BRCA1:c.4997dupA in our study was detected in one ovarian cancer patient and one breast cancer patient, and they both had one daughter with this mutation." (PMID 35205313, 2022).
breast cancer (continued). "Large deletions in BRCA1 have previously been shown to be associated with an increased risk of breast cancer risk (OR = 1.42) compared with carriers of BRCA1 pathogenic single nucleotide variants or Indels50." (PMID 36203093, 2022). "He had a sister with ovarian cancer and a germline BRCA1 mutation and a niece (the daughter of the sister with ovarian cancer) with breast cancer and a germline BRCA1 mutation." (PMID 36463295, 2022). "The cumulative evidence presented above suggested that HMMR overexpression increases BRCA1-associated breast cancer risk by further perturbing foundational process(es) that are altered in this type of cancer." (PMID 35393420, 2022). "Regarding risk perception and consistent with RQ2, beliefs that personal risk perception of breast cancer is higher than other people similar for age and gender were associated with higher intention to undergo genetic screening for BRCA1/2." (PMID 35448177, 2022). "60% of breast cancer patients carrying BRCA1 deleterious mutation were classified as triple-negative breast cancer, while only 10 to 20% were triple-negative breast cancer in unselected cancer patients." (PMID 36439508, 2022). "Hereditary breast cancers due to germline mutations in the breast cancer susceptibility genes BRCA1 and BRCA2 are very common." (PMID 35012580, 2022). "Women with pathogenic variants in BRCA1/2 diagnosed with breast cancer have up to 83% risk of developing contralateral breast cancer, which can take an average of 5.7 years to develop." (PMID 36685664, 2022). "In 3,388 breast cancer patients who underwent genetic testing for 25 genes, nearly half of the pathogenic variants were in the BRCA1 (24%) and BRCA2 (24.5%) genes." (PMID 35785170, 2022). "In summary, there is strong evidence indicating the essential role of progesterone-mediated RANK signaling in the expansion of a population of RANK+ luminal progenitors which are the likely cells of origin for BRCA1-associated basal-like breast cancers." (PMID 35418083, 2022). "Monotherapy was evaluated as a phase 1 study (NCT00892736) in patients with refractory BRCA1/2-mutated solid cancer; platinum-refractory ovarian, fallopian tube, or primary peritoneal cancer; or basal-like breast cancer." (PMID 35228986, 2022). "Consistent with this inhibitory role, BRCA1-deficient mammary tumor cells exhibited high levels of IRS-1." (PMID 35432218, 2022). "In 2016, BRCA1/2 germline mutations were screened in 5,931 unselected Chinese women with breast cancer, and this study found that the BRCA1 c.5470_5477del was the most common variant in this population." (PMID 35918668, 2022). "Progesterone-containing (but not estrogen-alone) hormone replacement therapy is associated with an increased risk of breast cancer in women with a BRCA1 mutation." (PMID 35418083, 2022). "Absence of adjuvant chemotherapy was the most powerful factor that was linked to a dramatic decline in survival for patients with breast cancer with BRCA1 and BRCA2 mutation." (PMID 36580360, 2022). "Using single-cell assays, in BRCA1 mutation breast cancer, basal-like breast cancer (ER-) and luminal breast cancer (ERhigh) respectively derive from luminal progenitors and mature luminal cells respectively." (PMID 36046046, 2022). "Loss of BRCA1 often leads to uncontrolled ER activity and consequently induces breast cancer formation or progression." (PMID 34996912, 2022). "One patient with a BRCA1 pathogenic variant was diagnosed with triple-negative, unilateral breast cancer when she was 72 years old." (PMID 35627717, 2022). "This is partially consistent with similar finding that the inheritance of defective BRCA1 or BRCA2 allele predisposes an individual to develop breast cancer." (PMID 36038839, 2022). "Under optimal conditions, we detected the breast cancer susceptibility gene 1 (BRCA-1), a representative cfDNA closely related to breast cancer." (PMID 35214994, 2022).